BCR (BCR activator of RhoGEF and GTPase)
Diseases named in the same sentence as BCR in open-access papers (continued):
Sharing a sentence is not in itself a finding about the gene and the disease.
chronic myeloid leukemia (continued). "We reported previously that 8-OHD provoked reactive oxygen species (ROS) overproduction, and induced autophagy, apoptosis, breakpoint cluster region-Abelson murine leukemia viral oncogene (BCR-ABL) degradation, and differentiation in K562 human chronic myeloid leukemia (CML) cells." (PMID 34944720, 2021). "In addition to its linkage with B-cell neoplasms, aberrant IκBα function was also detected in chronic myeloid leukemia (CML), a myeloproliferative disorder driven by the BCR-ABL translocation." (PMID 34572464, 2021). "The group suggested that EV‐DNA may have a physiological influence on the recipient cells, as they demonstrated EV‐DNA‐mediated transfer of a BCR/ABL hybrid gene, involved in chronic myeloid leukemia, to neutrophils and HEK293 cells." (PMID 32767659, 2021). "However, in chronic myeloid leukemia (CML), pDCs are derived from precursors that express a low level of BCR-ABL, and develop normally and usually express the co-stimulatory antigen CD86." (PMID 34737750, 2021). "In chronic myeloid leukemia cells, a complex formed by DNM2, Abelson helper integration site-1 (AHI-1) and the fusion oncogene BCR-ABL leads to activation of DNM2 through its phosphorylation by the BCR-ABL tyrosine kinase." (PMID 34294140, 2021). "Factors correlated with lower overall survival in patients with atypical chronic myelogenous leukemia, BCR/ABL1 negative." (PMID 34868917, 2021). "The abnormal expression of BCR/ABL may lead to many diseases, including chronic granulocytes leukemia, acute lymphocyte leukemia and the related pathways, including endometrial cancer and the PI3K/Akt pathway." (PMID 32955083, 2020). "Furthermore, function of the chimeric BCR-ABL gene seems to be key for initiation and maintenance of tumorigenicity, especially in chronic myeloid leukemia (CML)." (PMID 32370233, 2020). "Elevated expression of IGF-IR in BCR/ABL+ cells may promote the development and self-renewal of chronic myeloid leukemia, while downregulation of IGF-IR in BCR/ABL+ cells leads to acute lymphoblastic leukemia (ALL)." (PMID 32493414, 2020). "The best examples of the success of this screening method include the identification of the role of BCR and ABL as lethal hits in chronic myelogenous leukemia (CML) cell line KBM7, KRAS and PIK3CA and as lethal hits in colorectal cancer cell lines DLD-1 and HCT116." (PMID 30636933, 2019). "The lowest reported type was acute myeloid leukemia without maturation and chronic myelogenous leukemia, BCR/ABL positive (1.2% for each)." (PMID 31315607, 2019). "This fusion gene is a defining marker of chronic myeloid leukemia (CML) (96%) and breakpoints in the majority of samples occur in the 5.8-kb major breakpoint cluster region (between introns 11 and 16), resulting in a p210 BCR-ABL protein." (PMID 31007851, 2019). "Similarly, ABL1, part of the BCR-ABL target of imatinib, an early immunotherapy, had the top impact score in both datasets with chronic myeloid leukemia." (PMID 31479446, 2019). "Atypical BCR-ABL1 transcripts are detected in less than 5% of patients diagnosed with chronic myeloid leukaemia (CML), of which e19a2 is the most frequently observed, with breakpoints in the micro breakpoint cluster region (μ-BCR) and coding for the p230 BCR-ABL1 protein." (PMID 30526517, 2018). "In chronic myeloid leukemia (CML), where c-Myc is upregulated by BCR/ABL." (PMID 30261904, 2018). "Moreover, our previous study confirmed that oncoprotein BCR-ABL can elevate expression of AURKA and AURKB through Akt signaling pathway in chronic myelogenous leukemia (CML)." (PMID 28147341, 2017). "Recently, we applied smFISH to quantify the intra-tumor transcriptional heterogeneity of the oncogenic fusion gene, BCR-ABL, in chronic myeloid leukemia, and to study the cell-to-cell variability of immunoglobulin gene expression in follicular lymphoma cell lines." (PMID 28423635, 2017).
chronic myeloid leukemia (continued). "Second, unlike monogenic disorders such as chronic myeloid leukemia with the formation of the BCR-ABL fusion gene, MM is a complex polygenic trait shaped by multiple and translocation genetic anomalies, thus leading to a more obvious disease heterogeneity." (PMID 27129167, 2016). "AP24534 (Ponatinib) is a pan BCR–ABL, including BCR–ABLT315I, inhibitor used in the clinic to treat chronic myeloid leukaemia; however, AP24534 exhibits inhibitory activity towards VEGFR-2, FGFR-1 (fibroblast growth factor receptor-1), scr and Lyn (protein tyrosine kinase Lyn) kinases as well." (PMID 25757360, 2015). "Chronic myeloid leukemia (CML) is characterized by a balanced reciprocal chromosomal translocation involving the ABL1 gene on chromosome 9 and the BCR gene on chromosome 22, building the BCR-ABL1 fusion gene, which encodes for the constitutively activated tyrosine kinase (TK) BCR-ABL1." (PMID 26107505, 2015). "Imatinib, the first approved drug in this category, is an adenosine triphosphate, competitive inhibitor of KIT, PDGFRA, BCR-ABL, and ABL tyrosine kinases, which was already used in the treatment of patients with chronic myeloid leukemia (CML) who bear the BCR-ABL fusion gene." (PMID 26075122, 2015). "The BCR/ABL hybrid gene, involved in the pathogenesis of chronic myeloid leukemia (CML), could be transferred from K562 EVs to neutrophils and decrease their phagocytic activity in vitro." (PMID 25133686, 2014). "Exposure to the BRD4 inhibitor JQ1 sensitizes several leukemia cell lines but not the BCR/ABL1-positive chronic myelogenous leukemia cell line K562." (PMID 24576043, 2014). "Background and Objective: Breakpoint cluster region-Abelson (BCR-ABL) rearrangement or Philadelphia (Ph) chromosome in Chronic Myeloid Leukemia (CML) is derived from a reciprocal chromosomal translocation between ABL gene on chromosome 9 and BCR gene on chromosome 22." (PMID 25097530, 2014). "Moreover, in chronic myeloid leukemia, cytotoxic CD8+ T cells specific for a BCR-ABL fusion protein (resulting from the fusion of BCR and ABL genes) were found." (PMID 24860567, 2014). "Fusion genes are often oncogenes, such as BCR:ABL in chronic myeloid leukaemia (CML), TMPRSS2:ERG in prostate cancer, EML4:ALK in non-small-cell lung cancer (NSCLC) and so on." (PMID 24564548, 2013). "Early insight into the molecular pathogenesis of cancer stemmed from the discovery of activating oncogenes such as the Philadelphia chromosome positive (Ph+), and its constitutively active BCR-ABL protein tyrosine kinase product, in chronic myeloid leukemia (CML)." (PMID 22467334, 2012). "This occurs in chronic myeloid leukemia, where the BCR/ABL fusion oncoprotein is shown to positively regulate the expression of MICA/B at the translational level via a PI3K-dependent mechanism in the BCR/ABL+ cell line K562." (PMID 22046194, 2011). "The discovery of imatinib (Gleevec)—the drug targeting the kinase domain of the BCR-ABL fusion (BCR gene from chromosome 9 and ABL gene of chromosome 22) has revolutionized the management of chronic myeloid leukemia by significantly improving patient’s survival." (PMID 24281166, 2010). "In addition to the main BCR/ABL fusion transcripts, it has been reported that BCR/ABL transcripts, arising from alternative splicing, are also produced in a high percentage of chronic myelogenous leukemia (CML) and acute lymphoblastic leukemia (ALL) patients." (PMID 19516963, 2008). "The combination imatinib + γ-irradiation proved to be significantly synergistic over a broad range of cell growth inhibition levels in both BCR–ABL-positive cell lines and produced the strongest reduction in primary chronic myelogenous leukaemia colony-forming progenitor cells." (PMID 11986785, 2002).
chronic myeloid leukemia (continued). "To this purpose, we evaluated leukocyte counts and BCR::ABL1 quantitative expression either at diagnosis (baseline and no therapy) and on day 7 and day 14 of treatment in a cohort of 45 unselected patients with newly diagnosed chronic myeloid leukemia in the chronic phase." (PMID 40076467, 2025). "The Philadelphia chromosome, the translocation between BCR and ABL genes, is seen in 95% of chronic myeloid leukemia (CML) patients." (PMID 40114373, 2025). "Although miR-122-5p and CDC25A have been studied in several malignancies such as hepatocellular carcinoma and acute myeloid leukemia, their coordinated regulatory relationship within the molecular context of BCR::ABL1-positive chronic myeloid leukemia has not been previously characterized." (PMID 41373559, 2025). "Ponatinib, a third-generation TKI, targets the breakpoint cluster region (BCR) and Abelson (ABL) fusion protein, known as the oncoprotein BCR-ABL, in the management of Ph+ leukemia, including Ph+ B-cell acute lymphoblastic leukemia and chronic myeloid leukemia." (PMID 40678003, 2025). "Chronic myeloid leukemia (CML) is a myeloproliferative neoplasm characterized by bone marrow expansion and the proliferation of one or more myeloid cell lineages, predominantly driven by the expression of the constitutively active fusion product tyrosine kinase BCR:ABL1." (PMID 39051413, 2024). "In addition, unique BCR/ABL hybrid gene-containing EVs derived from human chronic myelogenous leukemia K562 cells were found to be transportable to HEK293 cells or neutrophils, resulting in the expression of the BCR/ABL hybrid gene mRNA and protein in the recipient cells." (PMID 39402599, 2024). "Chronic Myeloid Leukaemia (CML) is a model for modern precision medicine, where treatment is tailored to a patient's genetic profile.All CML patients exhibit the t (9:22) chromosomal translocation, resulting in the fusion of the BCR gene from chromosome 22 and the ABLkinase domain from chromosome 9." (PMID 40230905, 2024). "Chronic myeloid leukemia (CML) is a highly proliferative form of cancer derived from hematopoietic stem cells harboring the Ph chromosome and BCR::ABL fusion gene positivity as a result of the fusion of the ABL and BCR genes on chromosomes 9 and 22, respectively." (PMID 39573995, 2024). "DAS is a narrow therapeutic index drug and a novel tyrosine kinase multitarget inhibitor of the BCR-ABL and Src family of kinases was permitted for the treatment of chronic myelogenous leukemia (CML) by the US FDA, as well as for Ph+ ALL patients who could not tolerate first-line therapy." (PMID 36838589, 2023). "Incidence of chronic myeloid leukemia, BCR::ABL1–positive, (CML) in the general population accounts for 1–2 cases per 100.00 adults and about 15% of newly diagnosed cases of leukemia in adults." (PMID 36580136, 2023). "Chronic myeloid leukemia (CML) is a myeloproliferative neoplasm defined by the presence of the Philadelphia chromosome (Ph), which is a result of reciprocal translocation of the Abelson (ABL) gene on chromosome 9 and the breakpoint cluster region (BCR) gene on chromosome 22." (PMID 36168187, 2022). "Atypical chronic myelogenous leukemia (aCML), BCR/ABL1 negative is a rare disorder classified into the category of myelodysplastic/myeloproliferative neoplasms (MDS/MPN), according to the 2016 revision of the World Health organization (WHO) classification of myeloid neoplasms and acute leukemia." (PMID 34868917, 2021). "Therefore, miR-424 has been proposed as a tumor suppressor acting via down-regulation of BCR-ABL and its up-regulation may have a therapeutic effect in chronic myeloid leukemia." (PMID 28915608, 2017). "Chronic myeloid leukemia (CML) and Ph+ acute lymphoblastic leukemia (ALL) are characterized by the presence of the BCR-ABL oncoprotein, which leads to activation of a plethora of pro-mitogenic and pro-survival pathways, including the mTOR signaling cascade." (PMID 24260131, 2013).
chronic myeloid leukemia (continued). "Chronic myelogenous leukaemia (CML) is a clonal malignancy of the pluripotent haematopoietic stem cell, characterised by an uncontrolled proliferation and expansion of myeloid progenitors expressing a fusion oncogene, BCR-ABL, the molecular counterpart of the Ph1 chromosome." (PMID 15494718, 2004). "However, the present work found evidence that miR-7-5p may be related to chronic myeloid leukemia in a non-specific way, mainly considering its relationship with the BCR::ABL1 transcript." (PMID 38542337, 2024). "For example, ZMYM2::FGFR1 most commonly presents as a T-lymphoblastic leukemia/lymphoma, BCR::FGFR1 and TPR::FGFR1 present histologically similar to chronic myeloid leukemia (CML), and CEP43::FGFR1 and CNTRL::FGFR1 show features similar to chronic myelomonocytic leukemia (CMML)." (PMID 38611061, 2024). "A Deep Molecular Response (DMR), defined as a BCR::ABL1 transcript at levels ≤ 0.01% by RT-qPCR, is the prerequisite for the successful interruption of treatment among patients with Chronic Myeloid Leukemia (CML)." (PMID 37627140, 2023). "Blast crisis (BC) is an outcome that arises during the treatment process of chronic myeloid leukemia (CML), which is possibly attained by the dysregulation of the Notch and Ikaros signaling pathways, BCR-ABL translocation, redox, and inflammatory factors." (PMID 35815090, 2022). "Recently, our group determined whether the BCR/ABL1 copy number, expression, and/or activity were responsible for telomere maintenance and the deregulated expression of selected shelterin components (TRF1, TRF2, RAP1, and POT1) in widely used chronic myeloid leukemia (CML) cell lines." (PMID 34885080, 2021). "Imatinib, a tyrosine kinase inhibitor which is commonly used in the therapy of chronic myeloid leukaemia (CML) due to its inhibitory action on the chimeric BCR-ABL tyrosine kinase, is also a nonspecific inhibitor of the PDGF receptor and may reverse PH, as demonstrated in an experimental model." (PMID 32566097, 2020). "More recently, it was further demonstrated that ALOX5 is required for the induction of chronic myeloid leukemia (CML) by BCR-ABL, and a specific ALOX5 inhibitor is able to significantly delay CML onset when used either alone or in combination with the BCR-ABL kinase inhibitor imatinib." (PMID 24130502, 2013). "Furthermore, murine and human leukemic cells require glycolysis and combinatorial inhibition of CDK6 together with the glycolysis regulator 2-deoxy-D-glucose (2-DG) point at a novel therapeutic treatment strategy for BCR::ABL1+ ALL and chronic myeloid leukemia (CML) patients." (PMID 39966356, 2025). "In addition, Naito’s group developed BCR-ABL degraders PROTAC 23 and PROTAC 24 called SNIPER (ABL), which induced the degradation of BCR-ABL protein in BCR-ABL positive CML cells and inhibited the growth of chronic myeloid leukemia K562 cells." (PMID 36142231, 2022). "It is important to ensure that a blast crisis of chronic myeloid leukemia with an MPAL immunophenotype, post-cytotoxic therapy leukemia with an MPAL immunophenotype, and MPAL that has acquired BCR::ABL1 secondarily is not miscategorized as de novo MPAL with BCR::ABL1 fusion." (PMID 40075717, 2025). "Similarly, hematologic malignancies, including chronic myeloid leukemia, were ruled out with a normal leukocyte alkaline phosphatase (LAP) score and negative BCR-ABL test." (PMID 40062147, 2025). "However, those in the chronic phase, known as chronic myeloid leukemia (CML), rely on BCR-ABL TKIs and are mostly not at a great chance of infection until and unless they do not respond or have poor response to treatment and other multiple comorbidities." (PMID 35777011, 2022). "Based on our previous work in chronic myeloid leukaemia, we first analysed miR-17∼92 expression in ALL and observed a significantly lower expression in ALL as compared to normal CD34+ cells with further reduction in BCR-ABL-positive as compared to -negative ALL cells." (PMID 24280866, 2014).
leukemia (404 papers, 2004 to 2026). A malignant (clonal) hematologic disorder, involving hematopoietic stem cells and characterized by the presence of primitive or atypical myeloid or lymphoid cells in the bone marrow and the blood. "Co-inhibition of proteasomes and histone deacetylases eliminates TKI-refractory BCR::ABL1-driven leukaemia cells by inducing mitochondrial apoptosis and loss of clonogenic potential." (PMID 41696976, 2026). "A further study, however, found that therapy‐related leukaemias following treatment with radiation therapy alone had higher rates of BCR::ABL1 mutations compared to MLL." (PMID 40490854, 2025). "In the present study, we introduced the T315M mutation into the intrinsic BCR::ABL1 gene in three Ph + leukemia cell lines via HR using the CRISPR/Cas9 system." (PMID 40208408, 2025). "More than 70 mutations were reported in the BCR::ABL1 kinase domain (KD) in people with BCR::ABL1‐associated leukemias." (PMID 39440695, 2024). "This revolution in leukemia treatment is unfortunately accompanied by the fact that treatment interruption, in most cases, leads to the re-emergence of BCR-ABL-leukemia cells, caused by leukemia stem cells, that are insensitive to TKI treatment." (PMID 39199564, 2024). "We interrogated samples with BCR::ABL1‐positive ALL in several leukemia stages for ABL1 KD mutations using next generation sequencing (NGS)." (PMID 39440695, 2024). "Overexpression of BLM and RAD51 facilitates HRR and thereby causes resistance of BCR/ABL-positive leukemia cells to DNA damaging drugs." (PMID 38421735, 2024). "The translation of the BCR-ABL fusion gene produces a potentially pathogenic protein that plays a major role in oncogenesis of leukemia." (PMID 39457371, 2024). "For example, in CML some leukaemia cells carry a newly-mutated, resistant BCR::ABL1 fusion gene but mutated transcripts are undetectable by NGS." (PMID 38637690, 2024). "This implies the key pathogenic molecules and regulatory mechanisms caused by BCR-ABL in two types of leukemia are different." (PMID 36721266, 2023). "BCR/ABL fusion protein is the most critical disease-causing factor of CML leukemia and hence BCR/ABL inhibitors are the most suitable therapies for CML treatment." (PMID 38024167, 2023). "The most significant distinction between the two kinds of leukemia caused by BCR-ABL is that CML is related to excessive proliferation of mature myeloid cells, whereas Ph+ B-ALL is associated with blocked B lymphocyte differentiation." (PMID 36721266, 2023). "Several retrospective studies found that mutations in leukemia-associated genes in addition to BCR::ABL1 are not only a phenomenon seen in advanced or blast crisis CML but also in chronic phase CML." (PMID 35902731, 2022). "A drug resistant leukemia cell line was generated by introducing the T315I mutation into the BCR-ABL+ leukemia cell line using the CRISPR-Cas9 system." (PMID 36232600, 2022). "The major triggers for this type of leukemia are the BCR–ABL tyrosine kinase dysfunctions due to mutations or other causes." (PMID 35721186, 2022). "CML cells express both leukemia-specific antigen derived from the BCR-ABL fusion protein and leukemia-associated antigens, including Wilms tumor 1(WT1), proteinase 3 (PR1), and preferentially expressed antigen of melanoma (PRAME)." (PMID 34771599, 2021). "Somatic ABL1 missense variants associated with imatinib resistance in BCR-ABL leukaemias cluster exclusively within the kinase domain." (PMID 33223528, 2021). "Dexamethasone was unable to reverse the poorer survival of VD3 sufficient vs. deficient mice to BCR-ABL leukemia." (PMID 34669728, 2021). "Ponatinib, a third-generation TKI, is a potent BCR–ABL inhibitor in leukemia patients with both wild-type and BCR–ABL mutations, including T315I." (PMID 33762010, 2021). "Patients with Ph+ leukemia have a poor outcome and are, therefore, treated with high-risk regimens, including a tyrosine kinase inhibitor targeting the BCR/ABL-fusion." (PMID 34201368, 2021).